APOE (apolipoprotein E)
Diseases named in the same sentence as APOE in open-access papers (continued):
Sharing a sentence is not in itself a finding about the gene and the disease.
atherosclerosis (continued). "In ApoE knockout mice the IL-36γ can exert atherosclerosis-promoting effects by augmenting macrophage foam cell formation and uptake of oxidized low-density lipoproteins." (PMID 38961336, 2024). "IRF3 knockout significantly decreased the development of atherosclerosis in hyperlipidaemic ApoE-/- mice, which reduced necrotic core size, macrophage infiltration, lipids, and inflammation." (PMID 38164186, 2024). "In this research, we established high-fat diet (HFD)-induced ApoE−/− mice to investigate the potential mechanisms of T. fuciformis on atherosclerosis." (PMID 39796594, 2024). "Administration of recombinant sclerostin via intraperitoneal injection in ApoE knockout mice provides protection against atherosclerosis and inflammation." (PMID 38397878, 2024). "In vivo, ApoE−/− mice treated with Yoda1 exhibited regression of atherosclerosis, enhanced stability of advanced lesions, reduced plaque size and necrotic core, increased collagen content, and reduced expression levels of inflammatory markers." (PMID 39107572, 2024). "Endothelial GR knockout mice bred onto an ApoE null background showed worsened atherosclerosis compared to ApoE knockout mice alone." (PMID 38397878, 2024). "Bosentan treatment in diabetic, atherosclerotic ApoE-/- mice delayed the atherosclerosis progression and enhanced plaques' stability, showing modest but additive effects with atorvastatin, which are promising in atherosclerotic cardiovascular diseases." (PMID 38928320, 2024). "By contrast, a single systemic administration of Ang2 adenovirus, delivered directly into the tail vein of 8-week-old apoE−/− mice (atherosclerosis-prone), seems to reduce atherosclerotic lesions." (PMID 39769300, 2024). "Overall, the correlation between ApoE and atherosclerosis is well-established, with the protein playing a multifaceted role in lipid metabolism, inflammation, and atherogenesis." (PMID 39247623, 2024). "After 12 weeks of Western high-cholesterol diet, IR+/−/ApoE−/− had significantly more atherosclerosis in the thoracoabdominal aorta and at the level of the aortic sinus than ApoE−/− littermates." (PMID 39401163, 2024). "These lipid abnormalities, featured by increased levels of both TC and TG in the remnant lipoproteins, likely contribute to the development and progression of atherosclerosis in apoE KO rabbits." (PMID 39087075, 2024). "In conclusion, these findings suggest that the HMNVsM−D attenuates atherosclerosis in diabetic ApoE−/− mice in a metabolism independent manner." (PMID 38614985, 2024). "Initial studies have shown that Pon1−/− mice are highly susceptible to the toxicity of organophosphate insecticides and to atherosclerosis induced by the metabolic stress of a high-fat diet, or by ApoE depletion." (PMID 39594433, 2024). "Collectively, our data reveal that global LXN deletion protects ApoE-/- mice against atherosclerosis." (PMID 39424784, 2024). "An early study by Harja and collaborators demonstrated that RAGE-deficient ApoE−/− mice showed reduced markers of vascular inflammation in the aorta, which indicates the involvement of RAGE in the pathogenesis of atherosclerosis." (PMID 39194749, 2024). "Tetrahydroxy-stilbene-2-O-β-D-glucoside mitigates atherosclerosis in ApoE−/− mice, leveraging the modulation of intestinal microbiota." (PMID 38952541, 2024). "Tg26+/−/ApoE−/− mice developed accelerated atherosclerosis with a larger plaque area on a normal chow diet for 8 weeks compared with ApoE−/− mice." (PMID 38781301, 2024). "The present study aimed to explore the preventive effect of mussel oil (MO) on atherosclerosis and the potential mechanism in apolipoprotein E-null (ApoE−/−) mice." (PMID 38410635, 2024). "In ApoE-/- mice, atherosclerosis development is initiated spontaneously, even when animals are kept on a regular rodent diet, but it can be accelerated by applying a fat-enriched diet." (PMID 38474500, 2024).
atherosclerosis (continued). "A limitation of the APOE*3-Leiden.CETP mouse model is that only female mice develop atherosclerosis upon Western-type diet feeding." (PMID 38428154, 2024). "As heart failure promotes atherosclerosis progression in ApoE-KO mice, echocardiography was performed (n=5 (APOE-KO), n=4 (ApoE-KO; BAC/APOL1-G0 and ApoE-KO; BAC/APOL1-G1))." (PMID 39803526, 2024). "In this study we have utilized ApoE knockout mice to initially study the role of HIF-1α in myeloid cells in atherosclerosis." (PMID 39473019, 2024). "To elucidate these potential mechanisms, we used a pancreatic beta cell line (BTC6) and a mouse model of hyperglycemia-induced atherosclerosis, the ApoE−/−:Ins2+/Akita mouse, exhibiting sexual dimorphism in glucose regulation." (PMID 38339098, 2024). "In another case, by targeting collagen VI alpha 6 chain (COL6A6) with a specific human scFv, researchers achieved a 45% regression in atherosclerosis in ApoE−/− mice, evidenced by aorta staining." (PMID 39735545, 2024). "Ten weeks of BHB supplementation can ameliorate atherosclerosis by stabilizing Ca2+ homeostasis in the endoplasmic reticulum and modulating the subsequent inflammation via Grp109a in ApoE−/− mice." (PMID 39796543, 2024). "The series of incidences that result in plaque development in ApoE-/- mice is strikingly similar to that observed in well-researched bigger animal models of atherosclerosis as well as in humans." (PMID 38629090, 2024). "Inhibition of Nox2 using gp91dstat reduced atherosclerosis in the thoracoabdominal aorta of IR+/−/ApoE−/−." (PMID 39401163, 2024). "To definitively answer this question in an animal model of human insulin resistance before the onset of dysglycaemia we crossed mice haploinsufficient for the insulin receptor (IR+/−) with atherosclerosis-prone Apolipoprotein E holoinsufficient mice (ApoE−/−)." (PMID 39401163, 2024). "In line, NOX1/NOX4 pharmacological inhibition and Nox1 deficiency significantly attenuate vascular ROS levels and atherosclerosis burden in ApoE−/− mice." (PMID 38952543, 2024). "ApoE−/− mice have been extensively used for atherosclerosis studies because they spontaneously develop atherosclerotic lesions with characteristics similar to humans." (PMID 38794213, 2024). "Atherosclerosis rabbit models have become less common since the year 2000, when Apolipoprotein E (ApoE) became available and LDL receptor knock-out mice have been developed." (PMID 38629090, 2024). "This is similar to a previous study where gene expression of whole aortas from ApoE−/− vs WT animals were compared and corresponds to the well-known development of atherosclerosis in this mouse model." (PMID 38965173, 2024). "Research has demonstrated that the amount of Ly6Chi cells in the blood increases dramatically as atherosclerosis progresses in hypercholesterolemic ApoE-/- mice, suggesting that Ly6Chi monocytes have a crucial role in plaque progression." (PMID 39399488, 2024). "In our previous study, we discovered that suppressing Larp7 accelerates senescence by inhibiting Sirt1 activity, resulting in increased atherosclerosis in high‐fat diet (HFD) fed and ApoE deficient (ApoEKO) mice." (PMID 38818612, 2024). "Intracranial atherosclerosis was developed in apoE rabbits fed a CRD but WHHL rabbits, a model for human FH, exhibited more severe lesions than apoE KO rabbits." (PMID 39087075, 2024). "Studies have shown that insulin administration reduces the size of aortic atherosclerotic lesions in genetically modified mice, such as apolipoprotein E (ApoE) knockout mice, which are prone to atherosclerosis." (PMID 39125938, 2024). "CYP2J2 overexpression by adeno-associated virus injection increased the number of EETs and protected against HFD-induced atherosclerosis in ApoE-knockout mice." (PMID 38921429, 2024). "Their further studies found that TXNDC5 deletion in vascular endothelium result in increased eNOS protein and reduced atherosclerosis in apoE −/− mice." (PMID 38629066, 2024).
atherosclerosis (continued). "Under normal regular dietary conditions, apoE KO rabbits only exhibit mild elevation of plasma lipids, which is insufficient to induce atherosclerosis." (PMID 39087075, 2024). "Further studies indicate that apolipoprotein E-deficient (APOE (-/-)) mice exhibit PLIN2 gene inactivation, reducing LD numbers in foam cells within atherosclerotic lesions, potentially protecting against atherosclerosis." (PMID 39030618, 2024). "The adoptive transfer of Aza-iTreg significantly increased peripheral blood Treg cells, suppressed inflammation, and attenuated atherosclerosis in ApoE−/− mice." (PMID 39304654, 2024). "A study suggests the effects of several strains of Lactobacillus on atherosclerosis in ApoE-/- mice." (PMID 39439902, 2024). "Treatment of apolipoprotein E-deficient mice with an inhibitor of hyaluronan synthesis and hyaluronan degradation via the CD44 molecule damaged endothelial function and promoted atherosclerosis." (PMID 39728298, 2024). "For example, in ApoE-deficient mice, GIP analogs significantly reduced atherosclerosis and improved vascular function." (PMID 39263564, 2024). "We here used ApoE−/− mice, a model related to atherosclerosis, Alzheimer’s disease and other vascular diseases, and CNS dysfunction, and exposed them to a dose of 3 Gy, which is relevant to cancer therapy." (PMID 38891031, 2024). "In apolipoprotein E deficiency (ApoE−/−) mice with high-fat diet feeding, oral SAMB administration significantly attenuated inflammation and atherosclerosis plaque formation." (PMID 38839811, 2024). "Introduction of serum obtained from HSP60 immunised mice into ApoE−/− mice with induced atherosclerosis significantly increased plaque progression." (PMID 39194749, 2024). "Our previous studies have also shown that inhibiting glycosphingolipid synthesis reduces atherosclerosis and arterial stiffness in apolipoprotein E (−/−) mice and rabbits." (PMID 39456198, 2024). "In this study, CAP was shown to exacerbate atherosclerosis in HFD-fed apoE−/− mice, as evidenced by the increase in plaque size and volume in the aortic walls observed via Oil Red O staining." (PMID 38740741, 2024). "Six bacteria (Faecalibaculum, Defluviitaleaceae UCG, Streptococcus, Enterorhabdus, Bilophila, etc.)were differential gut microbiota biomarkers for camellia oil exerted anti-atherosclerosis effect against high-fat diet-induced ApoE−/− mice." (PMID 39403395, 2024). "further explored the effects of SMYAD on the pathological changes of atherosclerosis and the differentiation of monocytes, macrophages, and Tregs in ApoE-/- mice." (PMID 39582868, 2024). "Even if the diet is high in fat, the exogenously administered BHB reduces plaque volume in ApoE-/- mice, which inspired us about the feasibility about the long-term treatment of atherosclerosis with direct supplementation of BHB." (PMID 39075604, 2024). "ApoE−/− mice are a well-known and widely used model for research on atherosclerosis and liver steatosis." (PMID 36705799, 2024). "Transgenic mice carrying APOL1 (G0 and G1 variants) on bacterial artificial chromosomes (BAC/APOL1 mice) were crossed with the ApoE knock-out (ApoE-KO) atherosclerosis mouse model." (PMID 39803526, 2024). "Liraglutide in apoE−/− mice reduced body weight as well as suppressed macrophage-driven atherosclerosis." (PMID 39741663, 2024). "Considering endothelial injury and dysfunction were typical features of early atherosclerotic lesions, we detected Ash2l expression changes on the ECs of aortic sinus plaques from high-cholesterol diet-fed ApoE−/− mice, an animal model for atherosclerosis." (PMID 38280036, 2024). "ApoE-knockout (ApoE-/-) mice mimic traits of human atherosclerosis including inflammation and metabolism and are commonly used to simulate the effects of atherosclerosis and dyslipidemia." (PMID 38275616, 2024).
atherosclerosis (continued). "We fed ApoE-/- mice with high fat diet to establish atherosclerosis model, and used animal ultrasound machine to detect the artery of mice noninvasively." (PMID 38498570, 2024). "In an in vivo experiment, ApoE−/− mice were administered a PTP1B inhibitor to investigate the impact of PTP1B on atherosclerosis." (PMID 39517122, 2024). "Knockout of TNC also exacerbated the systemic inflammatory response and atherosclerosis by enhancing eotaxin (also named CCL11) levels in apoE-/- mice." (PMID 38164188, 2024). "To investigate the potential role of SRSF3 in inflammatory macrophages, we examined its expression in ApoE−/− mice, a widely used model for atherosclerosis." (PMID 38921043, 2024). "IMD also can improve metabolic syndromes such as obesity and insulin resistance in T1DM rats, T2DM mice, and ApoE−/− atherosclerosis mice." (PMID 39338366, 2024). "FGF21 inhibited atherosclerosis through mitigating Fas-mediated apoptosis in ApoE-/- mice, and in vitro studies have found that FGF21 inhibited apoptosis and prevented atherosclerosis progression in HUVEC through the Fas/FADD mechanism." (PMID 39558976, 2024). "Genetic inhibition of Nox2 leads to disruption of the aortic wall in IR+/−/ApoE−/− mice with accelerated atherosclerosis, whereas pharmacological Nox2 inhibition reduces atherosclerosis in IR+/−/ApoE−/− without disruption of the arterial wall." (PMID 39401163, 2024). "In order to define the phenotypes of arthritis mice combined with atherosclerosis, we applied ApoE−/− mice with K/BxN serum injection and HFD feeding to this study." (PMID 39716053, 2024). "IR+/−/ApoE−/−/Nox2−/y had significant disruption of the aortic wall with increased thoracoabdominal atherosclerosis when compared to IR+/−/ApoE−/−/Nox2+/y littermates." (PMID 39401163, 2024). "Among the first mouse models for atherosclerosis obtained through genetic engineering was the ApoE knockout model (Apoe−/−)." (PMID 38428154, 2024). "APOE-/- knockout germ-free (GF) mice fed either a fermentable fiber or a non-fermentable cellulose control diet were found to have reduced atherosclerosis in mice fed fermentable fiber." (PMID 38790227, 2024). "Since C57Bl/6 mice would not develop atherosclerotic lesions in the short period used in this study, atherosclerosis development was only evaluated in ApoE KO groups by quantifying fatty streaks in the aorta and more advanced lesions in the carotid artery." (PMID 39339767, 2024). "A similar expression pattern is visible in other inflammation and atherosclerosis related genes such as APOE, KLF4, CXC3L1, STC1, CH25H, and ABCG1." (PMID 39695567, 2024). "From all the significantly dysregulated genes in this model apolipoprotein E (ApoE) is highlighted due to its role in lipid metabolism, and its implications in inflammation, particularly in the context of atherosclerosis." (PMID 39247623, 2024). "For example, apoE is expressed in monocyte-derived macrophages and protects against atherosclerosis independent upon plasma lipids." (PMID 39087075, 2024). "The ApoE−/− mouse model is the most common mouse strain used to study atherosclerosis and is also useful for studying other diseases such as Alzheimer’s disease and respiratory diseases." (PMID 36904211, 2023). "Our previous study found that ANGPTL8 knockdown ameliorated atherosclerosis in ApoE−/− mice, whereas ANGPTL8 overexpression promoted plaque formation." (PMID 37294581, 2023). "For that purpose, transgenic (TG) mice over-expressing p190RhoGEF were cross-bred with atherosclerosis-prone apolipoprotein E (ApoE)−/− mice to obtain p190RhoGEF-TG mice with ApoE−/− backgrounds (TG/ApoE−/−)." (PMID 37628966, 2023).
atherosclerosis (continued). "When ApoE −/− mice (a murine model of atherosclerosis) were treated with choline and then resveratrol, TMAO synthesis was blocked." (PMID 36830968, 2023). "To examine the role of macrophages and lipid metabolism disruption in NP‐induced atherosclerosis, we exposed ApoE knockout (ApoE‐KO, ApoE−/−) mice to 50 nm PS‐NPs by daily oral gavage with a high‐fat diet (HFD) for 19 consecutive weeks." (PMID 37144527, 2023). "In the present study we have demonstrated a significant attenuation in the progression of established atherosclerosis in apoE−/− mice fed a HFD supplemented with nitrate." (PMID 36853380, 2023). "Moxonidine administration to ApoE−/− mice (18 mg/kg/day) decreased atherosclerosis formation in the aortic arch and left common carotid artery, associated with increased plasma lipid hydroperoxide levels." (PMID 36835270, 2023). "Apolipoprotein E also mediates subendothelial macrophage surface receptor-mediated endocytosis of remnants, which facilitates atherosclerosis." (PMID 37842298, 2023). "The aortic arch was the region of interest (ROI) within the ApoE-/- mouse where atherosclerosis had formed." (PMID 36766602, 2023). "Mesenchymal stem cells (MSCs)-derived exosomes have the ability to improve atherosclerosis in APOE−/− mice by decreasing the macrophage infiltration in the plaque through the miR-let7/ IGF2BP1/PTEN pathway." (PMID 37605155, 2023). "The adipose tissue-derived exosomes induce RAW264.7 macrophages to switch to the M1 phenotype, increase the secretion of pro-inflammatory cytokines (TNF-α, IL-6), and exacerbate atherosclerosis in hyperlipidemic ApoE−/− mice." (PMID 36683743, 2023). "Surprisingly, ApoE−/−;MC4RTB/TB mice also showed a higher incidence of AAA associated with atherosclerosis, increased proinflammatory genes, and immune-positive areas for F4/80 without Ang II administration." (PMID 37957201, 2023). "Of note, ICAM-1 expression is not only an EC activation marker, but it also mediates monocyte recruitment, vascular inflammation, and atherosclerosis, since ICAM-1 deficiency in ApoE–/– mice reduces atherosclerotic lesions." (PMID 36394956, 2023). "Here, we elucidated the anti-atherosclerotic effect and mechanism of ginger (Zingiber officinale Roscoe) essential oil (GEO) and its bioactive compound citral in Gubra Amylin NASH (GAN) diet with ʟ-carnitine-induced atherosclerosis female ApoE−/− mice." (PMID 37210385, 2023). "We demonstrated that blackberry polyphenols reduced oxidative stress and senescence in vascular smooth muscle cells (VSMCs) in vitro and that blackberry supplementation ameliorated atherosclerosis in ApoE−/− male mice in vivo." (PMID 36834497, 2023). "Beta-adrenergic receptor antagonism reduces accelerated atherosclerosis after TBI, as demonstrated in a mouse model deficient in apolipoprotein E." (PMID 38055768, 2023). "In the ApoE–/– HFD atherosclerosis model, the initial 6-week innate immune pathways (first wave) vanished, giving way to a distinct set of innate immune pathways at 32 weeks, which continued at 78 weeks (second wave)." (PMID 38327764, 2023). "For instance, in an apolipoprotein E (apoE)-knockout mouse model, MALAT1 deficiency accelerated inflammation and atherosclerosis." (PMID 37509544, 2023). "In contrast, the aortas of the ApoE-/- mice, an accepted animal model of atherosclerosis as a positive control, displayed the obvious atherosclerotic plaques formation." (PMID 36831235, 2023). "A commonly used mouse model of atherosclerosis is the Apolipoprotein E knock-out (ApoE) mouse fed a high fat diet (HFD)." (PMID 38151517, 2023).